RIPK2 (receptor interacting serine/threonine kinase 2)
Diseases named in the same sentence as RIPK2 in open-access papers (continued):
Sharing a sentence is not in itself a finding about the gene and the disease.
cancer (continued). "In the vast majority of 33 cancers, gene co-expression analysis showed that RIPK2 was positively correlated with the expression of immune checkpoint markers, such as PDCD1 (PD-1), CD274 (PD-L1), CTLA4 and TIGIT." (PMID 35508972, 2022). "The present study improves our understanding of the role of RIPK2 in the occurrence and development of malignant tumours, and it provides useful information for further in-depth study of RIPK2 and a theoretical basis for drug development." (PMID 35473583, 2022). "Together, these results indicate that RIPK2 is required for PC cell invasion and colony formation, key biological processes in cancer metastasis." (PMID 35115556, 2022). "In order to comprehensively explore the role of RIPK2 in cancer, we first analyzed the expression of RIPK2 in 33 tumors, and the result showed that RIPK2 was widely overexpressed in tumor tissues compared with normal tissues." (PMID 35508972, 2022). "In contrast, little is known about the molecular functions of RIPK2 in the metastasis of PC and other cancer types." (PMID 35115556, 2022). "Delineating the hierarchy between these kinases and RIPK2 will provide further insights into this protein functions in cancer metastasis." (PMID 35115556, 2022). "We obtained survival and prognosis information on RIPK2 expression in various cancer types through GEPIA2." (PMID 35473583, 2022). "Recent studies have shown that RIPK2 has a variety of mechanisms of action in malignant tumours and can affect sensitivity to chemotherapy and targeted drugs." (PMID 35473583, 2022). "The genetic alteration of RIPK2 in different cancers was investigated through cBioPortal, and we found that this genetic alteration was most pronounced in BRCA." (PMID 35508972, 2022). "Our results showed that RIPK2 was overexpressed in various tumor tissues, including GC, compared to non-cancer tissues." (PMID 33633788, 2021). "As expected, RIPK2 was overexpressed in various types of cancer tissues compared with corresponding normal tissues." (PMID 33633788, 2021). "In our study, first, we explored RIPK2 expression levels in cancers based on the oncomine and TCGA databases." (PMID 33633788, 2021). "The mechanism is still unclear what causes these links but the results presented lead us to suggest the possible use of RIPK2 as a therapeutic marker, which will shed light on the future development of anti-cancer therapies for KIRC." (PMID 33790054, 2021). "To verify the expression level of RIPK2 in human cancers, we analyzed RIPK2 expression based on TCGA data by TIMER." (PMID 33633788, 2021). "First, we explored the expression levels of RIPK2 in multiple cancers, including GC, using a bioinformatics approach." (PMID 33633788, 2021). "Previous studies showed that RIPK2 plays a role in tumor progression; however, these observations were limited to carcinomas of the breast, bladder and colon." (PMID 33633788, 2021). "Analysis of single-cell RNA-seq data from GSE111672 revealed that both MET and RIPK2 were expressed in cancer cells while RIPK2 was also expressed in monocytes and neutrophils." (PMID 33204717, 2020). "As we can see from scatter plots and bubble plots, both MET and RIPK2 were expressed in cancer cells and epithelial cells." (PMID 33204717, 2020). "As we can see from the scatter plots, both MET and RIPK2 are expressed in cancer cells, confirming the necessity to research their role in the development of PDAC." (PMID 33204717, 2020). "RIPK2 exhibits potential as a feasible target for immunotherapy in diverse cancers." (PMID 38164277, 2024). "The results indicated that RIPK2 expression was significantly linked to MSI in 33 different cancer types, with negative correlations observed in DLBC and KIPAN, and positive correlations observed in BRCA, BLCA, STAD, UCEC, THYM, STES, and SARC." (PMID 38164277, 2024). "Conversely, RIPK2 demonstrates heightened expression levels in most cancers." (PMID 38164277, 2024).
cancer (continued). "cancer-pku.cn/#general) have exactly illustrated that RIPK2 predominantly expresses in the human breast, skin, and lung tissues plus blood system, and is upregulated in various types of tumors, such as breast, ovarian, colon, esophagus, stomach, and pancreas cancers." (PMID 37324457, 2023). "In recent years, the relationship between RIPK2 and malignant tumours has attracted increasing attention, and there are an increasing number of reports on the relationship between RIPK2 and malignant tumours, especially the relationship between RIPK2 role in tumour occurrence and development." (PMID 35473583, 2022). "First, despite bioinformatics analysis provided us a preliminary insight of the crucial role of RIPK2 in cancer progression and immunotherapy resistance, biological experiments in vitro and in vivo are still needed to validate our findings and promote clinical transformation." (PMID 35508972, 2022). "In addition, our pan-cancer analysis showed that RIPK2-induced activity scores are strongly (rho = 0.88 on average) correlated with MYC activity scores across all the 32 cancer types." (PMID 35115556, 2022). "In addition, gene amplification is related to drug resistance, and RIPK2 has been shown to be amplified in most cancers." (PMID 35473583, 2022). "With the further study of RIPK2, there may be new findings or evidence that RIPK2 plays a role in cancer as a tumour suppressor gene." (PMID 35473583, 2022). "Therefore, the evidence suggested that immune infiltration was a mechanism by which RIPK2 promoted cancer progression." (PMID 35508972, 2022). "Therefore, the amplification of RIPK2 is a new research direction in the field of cancer treatment resistance." (PMID 35473583, 2022). "However, the role of RIPK2 in prognosis and immunotherapy response is yet to be elucidated in human pan-cancer." (PMID 35508972, 2022). "Therefore, the RIPK2/NF-κB signalling pathway is an important pathway to improve the sensitivity of chemoradiotherapy, targeted therapy and immunotherapy for malignant tumours." (PMID 35473583, 2022). "Moreover, the expression of RIPK2 was related to tumor classification in several cancers like LUAD, LUSC, THCA and multiple kidney cancers (KICH, KIRC and KIRP)." (PMID 35508972, 2022). "Therefore, we used the TCGA, CPTAC, HPA, and GEPIA2 databases or websites to conduct pancancer analysis of RIPK2, and explore the molecular mechanism and clinical prognosis of RIPK2 in cancer." (PMID 35473583, 2022). "In conclusion, to our knowledge we conducted the first comprehensive pan-cancer study of RIPK2." (PMID 35508972, 2022). "In addition, RIPK2 was positively associated with tumour-infiltrating immune cells (such as CD8+ T, Tregs, and cancer-associated fibroblasts)." (PMID 35473583, 2022). "In this study, comprehensive analysis was conducted based on various databases, we visualized the expression and prognostic value of RIPK2 in pan-cancer, and investigated its relationship to immunotherapy response, as well as its possible molecular biological functions." (PMID 35508972, 2022). "According to RNA expression data, RIPK2 is highly expressed in most cancer tissues, and RIPK2 may play an oncogenic role in cancer." (PMID 35473583, 2022). "RIPK2 plays an important role in the occurrence, development and prognosis of malignant tumours." (PMID 35473583, 2022). "In this study, we discovered that RIPK2 interacts with six protein kinases: MKK7 (MAP2K7), DNA-PKcs (PRKDC), RSK2 (RPS6KA3), MST4 (STK26), MEK2 (MAP2K2), and CSK (CSK), many of which were implicated in cancer metastasis." (PMID 35115556, 2022). "Another possibility is related to the difference in the expression of the RIPK2 gene itself, which may be highly expressed in all malignant tumours." (PMID 35473583, 2022). "Moreover, analysis of scRNA-seq data reveals that MET is expressed in cancer cells and epithelial cells while RIPK2 is expressed in cancer cells, epithelial cells, monocytes, and neutrophils." (PMID 33204717, 2020).
cancer (continued). "Thus, RIPK2 can play a role during inflammation injury in a number of disease settings, including cancer." (PMID 29874851, 2018). "Several genes (for example, RIPK2, EFNA4 and TMEM9B) showed differential expression in subtypes associated with high proliferation, such as IntClust 5 (predominantly HER2/ERBB2-amplified cancers) and IntClust 10 (predominantly basal expression type cancers)." (PMID 25572802, 2015). "RIPK2 also plays a significant role in various cancers and could act as a prognostic marker." (PMID 40406369, 2025). "Therefore, it is hypothesized that the regulation of tumor stemness by RIPK2 may have an impact on cancer progression, necessitating further investigation." (PMID 38164277, 2024). "Consequently, RIPK2 holds promise as a viable immunotherapy target for various types of cancer." (PMID 38164277, 2024). "Simultaneous inhibition of several proviral kinases by a single drug (i.e., “polypharmacology”), in this case the 3 catalytically active ErbBs and possibly STK10, RAF1, and RIPK2, may further increase the effectiveness while minimizing viral resistance, as previously shown in cancer." (PMID 37581931, 2023). "Together with the sample analysis result that the activity score of RIPK2 is highly correlated with c-Myc activity scores in clinical tissue specimens of 32 cancer types, we speculate that RIPK2 could also be a potential target for HCC treatment with high reliability." (PMID 37324457, 2023). "Besides PC, RIPK2 is frequently genetically altered in several other cancers, its overexpression is associated with shorter overall survival in nine cancer types, and its activity scores are highly correlated with MYC activity scores across 32 cancer types." (PMID 35115556, 2022). "However, whether RIPK2 plays the same role in other cancers is unclear and needs to be further investigated." (PMID 35473583, 2022). "In addition,RIPK2 may be used as a new molecular marker and prognostic factor for cancer, especially for those tumour types with poor prognosis and special molecular types, indicating the need for further study." (PMID 35473583, 2022). "Therefore, RIPK2 might play a vital role in overactive inflammatory responses observed in various diseases, including cancer." (PMID 33633788, 2021). "Interestingly, the use of RNA interference (RNAi) showed that RIPK2 knockdown could significantly alter cancer cells chemosensitivity." (PMID 29874851, 2018). "RIPK2 promotes metastasis by activating MKK7 and stabilizing c-Myc, making its inhibition a potential therapeutic strategy for cancer prevention." (PMID 40406369, 2025). "Several of these diseases have links to inflammation and/or cancer, thus highlighting the importance of the NOD2/RIPK2 pathway." (PMID 40095546, 2025). "HOIP participates in NF-κB signaling, cell death, inflammation, immunity, and cancer by conjugating linear ubiquitin chains onto a few proteins, such as RIPK1, RIPK2 and NEMO4–7." (PMID 38582895, 2024). "To effectively predict survival, we screened two inflammation-related genes (RIPK2 and NOD2) that were highly expressed in cancer tissues and which influenced clinical outcomes." (PMID 38742117, 2024). "Then, the correlation between RIPK2 and immune infiltration, immune score, stromal score, and ESTIMATE score was investigated in the Cancer Genome Atlas (TCGA) and tumor immune estimation resource (TIMER) databases." (PMID 35508972, 2022). "F. nucleatum can also invade ESCC cancer cells and promote cancer progression through the NOD1/RIPK2/NFκB pathway." (PMID 36033476, 2022).
cancer (continued). "Among these candidate molecular targets, nine were significantly enriched in all three cohorts, and five of them (TP53BP1, RIPK2, EHMT2, IGFBP3, and HMOX1) have been reported to have cancer- and chemoresistance-promoting activities simultaneously." (PMID 35606881, 2022). "At present, the relationship of RIPK2 with GZMB, NKG7 and PRF1 in cancer is still unclear, and this still needs to be explored in the occurrence, development, treatment and prognosis of cancer." (PMID 35473583, 2022). "We found that RIPK2 was positively correlated with CD8+ T, T regulatory cells, and cancer-related fibroblasts in most cancers, whereas in BRCA, RIPK2 is negatively correlated with cancer-related fibroblasts." (PMID 35473583, 2022). "In order to further research the mechanism of how MET and RIPK2 promote the progression of PDAC, we predict that the role of these two genes in cancer is to promote autophagy and took these two genes as central nodes to construct a probable regulatory network." (PMID 33204717, 2020). "The development of cancer has been the subject of extensive research, with a total of 615 papers examining the effects of RIPK1, 119 papers investigating the effects of RIPK2, 550 papers exploring the effects of RIPK3, and 54 papers analyzing the effects of RIPK4." (PMID 38164277, 2024). "The RIPK2 expression on a large cohort of CRC patients was found significantly increased in the cancer group, non-significantly higher expression in the metastatic group, and non-significantly lower expression in the KRAS-positive group." (PMID 37869102, 2023). "Moreover, RIPK2 affected immune score, stromal score and ESTIMATE score for a wide range of cancers." (PMID 35508972, 2022). "Thus, the findings indicate that the co-amplification/gain of RIPK2 and MYC, a frequent event in PC and several other cancer types, synergistically contributes to c-Myc protein abundance independent of the cellular context." (PMID 35115556, 2022). "Although the role of RIPK2 in cancer is increasingly reported, there is no systematic study of RIPK2’s function and clinical importance in human pan-cancer." (PMID 35508972, 2022). "Frequent RIPK2 and MYC co-amplification/gain also occurs in several other cancer types." (PMID 35115556, 2022). "From the lncRNA-mRNA pathway network, PYCARD, RIPK2, and CASP1 were found to be significantly enriched in the NOD-like receptor signaling pathway, whereas MAP2K2, LUM, RPS6, PDCD4, TWIST1, and HIF1A were significantly enriched in proteoglycans in cancers." (PMID 36619896, 2022). "The protein subnetwork of PIK3R2 could be used for further pan-cancer studies in the future: DUSP10, DUSP6, FHL2, IRS2, PIK3R2, and RIPK2." (PMID 36329531, 2022). "Therefore, we used the QUANTISEQ, XCELL, MCPCOUNTER and EPIC methods to analyse the relationship between RIPK2 and CD8+ T, T regulatory cells and cancer-related fibroblasts." (PMID 35473583, 2022). "In addition, the survival analysis emphasized the prognostic significance of TRAFD1, SOD2, RIPK2, RBCK1, and MT2A as cancer-promoting factors in ccRCC and pRCC." (PMID 34795663, 2021). "Even though these type II kinase inhibitors are approved anti-cancer medications (their corresponding AR can be accessed by following the links for ponatinib, regorafenib, and sorafenib), the broad kinase selectivity of these drugs prohibited their application as RIPK2 inhibitors in clinics." (PMID 36959850, 2023). "We further compared the relative expression of these molecules in 14 cancer types containing paired tumor and normal samples and found that approximately half of the autophagy regulators showed elevated expression in different cancers, including BIRC5, RIPK2, MET, ITGA6, BCL2L1, CASP4, etc.." (PMID 36261830, 2022).
cancer (continued). "In our proposed DMD-related lncRNA-mRNA pathway networks, PYCARD, RIPK2, and CASP1 were significantly enriched in the NOD-like receptor signaling pathway, whereas MAP2K2, LUM, RPS6, PDCD4, TWIST1, and HIF1A were significantly enriched in proteoglycans in cancers." (PMID 36619896, 2022). "Importantly, phosphorylation cascade is a highly effective strategy for signal amplification, which may explain why RIPK2 and MYC activity scores are strongly correlated in PC and many other cancer types." (PMID 35115556, 2022). "Therefore, RIPK2 is negatively correlated with cancer-related fibroblasts in BRCA, which may inhibit the invasion and metastasis of BRCA, suggesting that RIPK2 plays a different role in malignant tumours." (PMID 35473583, 2022). "Most structural studies have focused on the RIPK2 KD because the functions of KD are independent of the CARD, and kinase inhibitors are well-established therapeutic agents in cancers and inflammatory diseases." (PMID 36959850, 2023). "So far there is no targeted therapy for RIPK2 in cancer in general and, hence, in CRC; however, several RIPK2 inhibitors have been under investigation in several inflammatory diseases." (PMID 34356990, 2021).